MBNL2 (muscleblind like splicing regulator 2)
Description:
Mediates pre-mRNA alternative splicing regulation. Acts either as activator or repressor of splicing on specific pre-mRNA targets. Inhibits cardiac troponin-T (TNNT2) pre-mRNA exon inclusion but induces insulin receptor (IR) pre-mRNA exon inclusion in muscle. Antagonizes the alternative splicing activity pattern of CELF proteins. RNA-binding protein that binds to 5'ACACCC-3' core sequence, termed zipcode, within the 3'UTR of ITGA3. Binds to CUG triplet repeat expansion in myotonic dystrophy muscle cells by sequestering the target RNAs. Together with RNA binding proteins RBPMS and RBFOX2, activates vascular smooth muscle cells alternative splicing events (By similarity). Regulates NCOR2 alternative splicing (By similarity). Seems to regulate expression and localization of ITGA3 by transporting it from the nucleus to cytoplasm at adhesion plaques. May play a role in myotonic dystrophy pathophysiology (DM).
Synonyms: MBLL; MBLL39; PRO2032
Tractability: PROTAC: ubiquitination databases record sites on it.
Gene: Protein-coding gene on chromosome 13 (97,221,434 to 97,394,121, forward strand). Ensembl gene ENSG00000139793.
Subcellular location: Nucleus; Cytoplasm
Subcellular location (Human Protein Atlas): Nucleoplasm
Gene Ontology:
Molecular function: RNA binding; sequence-specific double-stranded DNA binding; metal ion binding
Biological process: regulation of RNA splicing
Cellular component: cytoplasm; nucleoplasm; nucleus
Genetic constraint (gnomAD): Loss-of-function variants: 9 observed, 28.09 expected, observed/expected ratio (o/e) 0.32, 90% interval 0.19 to 0.56. The upper end of that interval is the gene's LOEUF score, 0.56, which puts it in group 2 of 6, group 1 being the genes least tolerant of losing a copy. Missense variants: 273 observed, 428.65 expected, observed/expected ratio (o/e) 0.64, 90% interval 0.58 to 0.7. Synonymous variants: 167 observed, 157.28 expected, observed/expected ratio (o/e) 1.06, 90% interval 0.94 to 1.21.
Homologues: Orthologues: chimpanzee MBNL2 (100% identical), dog MBNL2 (99% identical), rabbit MBNL2 (99% identical), pig MBNL2 (98% identical), guinea pig MBNL2 (95% identical), macaque MBNL2 (91% identical), mouse Mbnl2 (88% identical), rat Mbnl2 (88% identical), tropical clawed frog mbnl2 (86% identical), zebrafish mbnl2 (74% identical), Drosophila melanogaster mbl (42% identical), Caenorhabditis elegans mbl-1 (21% identical). Paralogues in human: MBNL1 (65% identical), MBNL3 (57% identical), ZC3H10 (19% identical).
Diseases named in the same sentence as MBNL2 in open-access papers:
MBNL2 is named in the same sentence as 48 diseases in open-access papers, as found by Europe PMC text mining. Sharing a sentence is not in itself a finding about the gene and the disease. The quoted sentences say what the papers report.
myotonic dystrophy (10 papers, 2013 to 2026). An inherited progressive disorder affecting the muscles. "Taken together, our findings indicate that loss of MBNL2 function affects GABAergic function in a mouse model of myotonic dystrophy (DM1)." (PMID 36150891, 2022). "The association of MBNL2 and the myotonic dystrophy has been reported in the literature where the MBNL2 knockout mice were able to recapitulate cardinal features of myotonic dystrophy." (PMID 32652860, 2020). "For example, we detected a dMEP of exons in MBNL2, a gene implicated in the development of myotonic dystrophy that overlaps a targeted haplotype block associated with alcoholism (rs9556711) on chromosome 13." (PMID 31031799, 2019). "MBNL2 participates in alternative splicing, polyadenylation, and mRNA localization in neurons, and its inhibition is linked with RNA-mediated disease myotonic dystrophy." (PMID 28928394, 2017). "In fact, depletion of specific splicing factors, including Mbnl2, is thought to be a major cause of myotonic dystrophy because it results in dysregulation of splicing in specific transcripts." (PMID 27684375, 2016). "MBNL1 and MBNL2 are both required for late myogenic maturation in human skeletal muscle cells, and knockout of either Mbnl1 or Mbnl2 in mice serves as a model for myotonic dystrophy." (PMID 40944391, 2026). "The muscleblind-like 2 (MBNL2) splicing regulator, a member of the MBNL family of RNA-binding proteins, has been implicated in the neurological symptoms of myotonic dystrophy." (PMID 39764514, 2024). "In human, MBNL proteins, encoded by three members MBNL1, MBNL2 and MBNL3, are key splicing factors in the neuromuscular disease myotonic dystrophy (DM)." (PMID 23685613, 2013). "In mice, both brain-specific knockout of MBNL1 and MBNL2 and brain-specific expression of expanded CUG RNA in the myotonic dystrophy model resulted in the reduction of dendritic complexity and alteration of postsynaptic morphology." (PMID 39423233, 2024).
Myotonia (9 papers, 2008 to 2024). An involuntary and painless delay in the relaxation of skeletal muscle following contraction or electrical stimulation. "Because myotonia was more severe following the depletion of Mbnl2, we first compared the Clcn1 splicing pattern in WT, Mbnl1 KO and Mbnl1−/−; Mbnl2+/− KO skeletal muscle." (PMID 24293317, 2013). "However, they found that Mbnl1−/−/Mbnl2+/− were viable (albeit with reduced survival), smaller in size, and had increased myotonia, weakness, and severe myopathy by 8–12 weeks of age." (PMID 38473933, 2024). "Although Mbnl1−/−; Mbnl2−/− double knockouts (DKOs) are embryonic lethal, Mbnl1−/−; Mbnl2+/− mice are viable but develop cardinal features of DM muscle disease including reduced lifespan, heart conduction block, severe myotonia and progressive skeletal muscle weakness." (PMID 24293317, 2013). "Thus, Mbnl1−/−; Mbnl2+/− KOs recapitulate DM-relevant muscle weakness/wasting and myotonia." (PMID 24293317, 2013). "More recently, the generation of a Mbnl2-deficient mouse also displaying myotonia, skeletal muscle pathology consistent with human DM, and reduced expression of CLC-1 mRNA in skeletal muscle, suggests that depletion of MBNL2 might also contribute to the human DM pathogenesis." (PMID 19516957, 2008). "In DM1 and DM2 individuals without clinical myotonia, splicing of MBNL2, MBNL1, CLASP1, and MAP3K4 showed changes intermediate between those with myotonia and UA subjects." (PMID 30254196, 2018).
hepatocellular carcinoma (7 papers, 2016 to 2022). A malignant tumor that arises from hepatocytes. "In Axis 4, miR-493-5p↓ ZIC2↑ MBNL2↑, MBNL2 is abnormally expressed in lung and breast cancer, as well as hepatocellular carcinoma." (PMID 34805186, 2021). "MBNL2 is reported to inhibit tumor growth and invasion in hepatocellular carcinoma; however, the molecular mechanism beyond the anti-tumor effect of MBNL2 is mainly unknown." (PMID 33466733, 2021). "Based on deep sequencing analysis of the transcriptomes of epithelial and mesenchymal cells, results from previous study revealed that MBNL2 altered the splicing of EMT-associated regulators and suppressed cell proliferation, tumorsphere formation, and migration in hepatocellular carcinoma in vivo." (PMID 31320607, 2019).
breast carcinoma (5 papers, 2019 to 2022). "We detected MBNL2 protein expression by immunohistochemistry in commercial tissue microarrays which containing cancer tissues of patients with primary operable breast cancer, lung cancer, or liver cancer and adjacent normal tissues." (PMID 34659561, 2021). "A significant downregulation of MBNL2 was observed in several cancer types, including breast cancer, liver cancer, lung adenocarcinoma, and lung squamous cell carcinoma." (PMID 34659561, 2021). "Because MBNL2 is downregulated in breast cancer tissues, we further identified MBNL2-targetting miRNAs which were upregulated in breast cancer." (PMID 34659561, 2021). "The number of MBNL2-targeting miRNAs that were up or down regulated in breast cancer is represented in Venn diagrams." (PMID 34659561, 2021). "To identify the upstream signals responsible for downregulation of MBNL2 in cancer, we explored the MBNL2-targeting miRNAs upregulated in breast cancer tissues using TCGA miRNA-seq data." (PMID 34659561, 2021). "MBNL2 possesses antitumor activity in lung and breast cancers and can inhibit cancer cell metastasis via the pAKT/EMT signaling pathway." (PMID 33193734, 2020). "MBNL2 overexpression mimicked the effect of NBT on breast cancer and lung cancer cell motility and metastasis, in addition significantly enhanced the inhibition effect of NBT." (PMID 31320607, 2019). "To this end, we knocked down MBNL2 expression by using shRNA, or overexpressed His-MBNL2 in MDA-MB-231 breast cancer cells, A549 non-small-cell lung cancer cells, and HepG2 liver cancer cells, the knock-down or knock-in efficiency were verified by qRT-PCR and western blot." (PMID 34659561, 2021). "Finally, we obtained 9 MBNL2-targeting miRNAs that were upregulated in breast cancer, including miR-182, miR-429, miR-97, miR-33a, miR-183, miR-200c, miR-493, miR-200b and miR-32." (PMID 34659561, 2021). "To further study the molecular mechanism of MBNL2 on EMT, we performed gene coexpression analysis using the Oncomine breast cancer databases." (PMID 34659561, 2021). "Interestingly, MBNL2 has been recently reported to control hypoxia response in breast cancer cells and PCDH7 was reported to induce bone metastasis of breast cancer cells." (PMID 35697736, 2022). "We found that MBNL2 was lower expressed in both breast carcinoma and lung adenocarcinoma compared to the non-cancerous tissues." (PMID 31320607, 2019).
lung carcinoma (5 papers, 2007 to 2022). "MBNL2 controls lung cancer cell responses to hypoxia by regulating the expression and alternative splicing of hypoxia-induced genes." (PMID 36118863, 2022). "It was also found that MBNL2 expression was significantly upregulated in breast and lung cancer cells following treatment with a natural compound, Neobractatin (NBT), and overexpression of MBNL2 inhibited tumor metastasis." (PMID 34948025, 2021). "We show that MBNL2 is downregulated in breast, liver and lung cancers, overexpression of MBNL2 inhibits cancer cell metastasis by modulating PI3K/AKT mediated EMT process." (PMID 34659561, 2021). "This study suggest that NBT possesses significant antitumor activity in breast and lung cancer cells that is partly mediated through the MBNL2 expression and enhancement in metastasis via the pAKT/EMT signaling pathway." (PMID 31320607, 2019). "The microarray data from GEO also showed downregulation of MBNL2 in breast and lung cancer tissues." (PMID 34659561, 2021). "Therefore, we hypothesized that MBNL2 might function as a tumor suppressor in breast, liver and lung cancers." (PMID 34659561, 2021).
myotonic dystrophy type 1 (4 papers, 2016 to 2026). Steinert disease, also known as myotonic dystrophy type 1, is a muscle disease characterized by myotonia and by multiorgan damage that combines various degrees of muscle weakness, arrhythmia and/or cardiac conduction disorders, cataract, endocrine damage, sleep disorders and baldness. "Hnrnpl knockdown results in significant downregulation of Mbnl2 and upregulation of Mbnl1, two splicing factors that are linked to myotonic dystrophy type 1 (DM1)." (PMID 40944391, 2026). "Considerable evidence from mouse models and human postmortem brain suggests loss of Muscleblind-like protein 2 (MBNL2) function in brain is a major driver of CNS symptoms in Myotonic dystrophy type 1 (DM1)." (PMID 36150891, 2022). "Aberrant alternative splicing of MBNL1 and MBNL2 is characteristic of the foetal splice pattern reported in patients with the severe neuromuscular disease myotonic dystrophy type 1 (DM1; OMIM#160900)." (PMID 31116797, 2019). "MBNL1 and MBNL2 associate and bind to expanded CUG and CAG repeats, which accumulate as discrete nuclear foci in both DM1 and DM2 (myotonic dystrophy type 1 and type 2), therefore suggesting their implication in these disorders." (PMID 27465358, 2016).
liver cancer (3 papers, 2016 to 2025). An epithelial or non-epithelial malignant neoplasm that arises from the liver. "We report here that MBNL2 is downregulated in breast, lung and liver cancer tissues, the promoter methylation levels of MBNL2 are higher in cancer tissues than normal tissues." (PMID 34659561, 2021). "To explore the biological function of MBNL2 in cancer, we identified the top 1000 MBNL2 correlated genes from TCGA breast, lung and liver cancer data sets and the gene lists were submitted to Metascape to perform gene ontology enrichment analysis." (PMID 34659561, 2021). "Depletion of MBNL2 promotes whereas exogenous MBNL2 inhibits migration and invasion in breast, lung and liver cancer cells." (PMID 34659561, 2021). "An analysis of MBNL2 expression in human liver cancer cell lines showed that MBNL2 was expressed at low levels in Hep-J5 cells and at high levels in Huh7 cells." (PMID 27564110, 2016). "We observed that MBNL2 is down regulated in breast, lung, and liver cancer." (PMID 34659561, 2021). "Muscleblind-like splicing regulator 2 (MBNL2), a member of the MBNL family of RBPs, is down-regulated in breast, lung, and liver cancer tissues." (PMID 40271197, 2025).
renal cell carcinoma (3 papers, 2024 to 2025). "In renal cell carcinoma, CCL2 secreted by M2 macrophages increases muscleblind like splicing regulator 2 (MBNL2) expression, which in turn stabilizes B-cell lymphoma 2 (Bcl-2) mRNA, leading to the inhibition of Beclin 1-dependent autophagy and endowing RCC cells with invasion properties." (PMID 39286635, 2024).
cognitive deficits (2 papers, 2021 to 2022). "Except for treating sleep-related disorders, in Mbnl2–/– mice, mirtazapine, a kind of antidepressant, has been discovered to reverse cognitive impairments and depression, as well as reduce microglia and neuronal loss." (PMID 34867280, 2021). "Using conditional Mbnl2NEX-cKO mice (a tissue-specific knockout mouse model lacking the Mbnl2 gene in forebrain glutamatergic neurons), long-term cognitive impairment and depression were found." (PMID 34867280, 2021).
heart failure (2 papers, 2024 to 2025). Inability of the heart to pump blood at an adequate rate to meet tissue metabolic requirements. "MR analysis identified significant causal associations between the genes implicated in BW loss (ADD3, HSPA12A, SLC18A2, PDZD8, DUSP5, CASP7) as well as EF% and LV volumes (GPC6, UGGT2, SLAIN1, POU4F1, MBNL2) in BXD mice post-DOX and heart failure (HF) outcomes in humans." (PMID 40321772, 2025).
left ventricular hypertrophy (2 papers, 2013 to 2016). Enlargement of the LEFT VENTRICLE of the heart. "MRI analysis of Mbnl1−/−; Mbnl2+/− KOs revealed atrial dilatation and left ventricular hypertrophy." (PMID 24293317, 2013).
Brain atrophy (1 paper, 2021). Partial or complete wasting (loss) of brain tissue that was once present. "Thus, Mbnl1 heterozygosity, in conjunction with Mbnl2 loss, results in global brain atrophy with increased apparent ventricle volumes and widespread white and gray matter volume reductions in the mouse brain at four months of age." (PMID 34848815, 2021).
breast tumor (1 paper, 2019). "In summary, MBNL2 overexpression combined with NBT inhibited metastasis in the breast tumor in vitro and in vivo to a larger extent than either treatment alone." (PMID 31320607, 2019).
colon cancers (1 paper, 2022). "Accordingly, in patient-derived colon cancers stratified according to their consensus molecular signature, the same QKI, RBM24, and MBNL2 genes were found to have increased expression in CMS4 tumors, known for their pronounced mesenchymal composition and poor prognosis." (PMID 36346211, 2022).
diabetes (1 paper, 2024). "Knockout of the MBNL2 gene in mouse models has been associated with diabetes-related characteristics in the central nervous system, including abnormal rapid eye movement sleep tendencies and spatial memory deficits." (PMID 38919616, 2024).
dilated cardiomyopathy (1 paper, 2025). Cardiomyopathy which is characterized by dilation and contractile dysfunction of the left and right ventricles. "In addition, upregulation of Kcna4 and downregulation of Ckmt2, genes linked to dilated cardiomyopathy and arrhythmia, have been observed in cardiac-specific MBNL1 and MBNL2 double-knockout mice and were also misregulated in CUG960 +dox mice." (PMID 39932794, 2025).
laminopathies (1 paper, 2012). "We examined the effect of mutant TMEM43 on mRNA expression of four genes, LMO7, KCTD12, MBNL2 and RAP2A, located on chromosome 13, that have been shown to have abnormal expression in the setting of laminopathies with striated muscle dysfunction." (PMID 22458570, 2012).
leukemia (1 paper, 2020). A malignant (clonal) hematologic disorder, involving hematopoietic stem cells and characterized by the presence of primitive or atypical myeloid or lymphoid cells in the bone marrow and the blood. "In both Mbnl1+/+ and Mbnl1−/− states Mbnl2 and Mbnl3 are stably expressed in mouse leukemia cells, however neither analogue was meaningfully expressed in the human leukemia lines assayed." (PMID 32398749, 2020). "Therefore, one possible explanation for the eventual development of leukemia in our Mbnl1−/− murine model is that Mbnl2 compensates for the absence of Mbnl1, but it is unclear if this compensatory mechanism would necessarily behave similarly in human cells." (PMID 32398749, 2020).
medulloblastoma (1 paper, 2023). A malignant, invasive embryonal neoplasm arising from the cerebellum. "Of these seven genes (LTBP1, MAP1A, MBNL2, LGALS1, PNRC1, DAB2, and PLAAT3), only one, LGALS1, had been researched previously in relation to medulloblastoma, where it is up-regulated in MBSHH patients and activated by the SHH signalling pathway." (PMID 36831428, 2023).
melanoma (1 paper, 2025). A malignant, usually aggressive tumor composed of atypical, neoplastic melanocytes. "We generated CRISPR-Cas9 knockout models of Mbnl1 (“1KO”) and Mbnl2 (“2KO”) in B16-F10 melanoma cells." (PMID 40305509, 2025). "In mouse melanoma, this was first revealed through a CRISPR knockout screen, where Mbnl1 and Mbnl2 emerged as top hits conferring tumor resistance to cytotoxic T cell-mediated killing." (PMID 40305509, 2025).
mitral valve prolapse (1 paper, 2015). A fairly common and often benign valvular heart disorder characterized by redundancy or hooding of mitral valve leaflets so that they prolapse into the left atrium, often causing mitral regurgitation. "Suggestively, MBNL2 is one of sixteen genes within a locus on chromosome 13 that has been genetically linked with mitral valve prolapse, although to date no studies have corroborated a role for MBNL2 in valve disease." (PMID 26472242, 2015).
Ventricular hypertrophy (1 paper, 2015). Enlargement of the cardiac ventricular muscle tissue with increase in the width of the wall of the ventricle and loss of elasticity. "Restoring MBNL2 to near wild type levels in Mbnl1-null mice by removal of one Mbnl2 allele was sufficient to induce atrial dilation, ventricular hypertrophy, and conduction defects." (PMID 26472242, 2015).